TLR3 (toll like receptor 3)
Diseases named in the same sentence as TLR3 in open-access papers (continued):
Sharing a sentence is not in itself a finding about the gene and the disease.
viral infection (continued). "Interestingly, infection with both viruses markedly promoted the expression of TLR1 and TLR2, which are sensors of bacterial components, which may be explained by the up-regulation of IFNα and IFNγ that could enhance the expression of TLR1, TLR2, TLR3, and TLR7 in viral infections." (PMID 27916934, 2016). "Therefore, it appears that TLR3 may provide some protection against acute or virulent viral infections but not against non-virulent viral infections." (PMID 22189096, 2011). "Virus infection further enhanced YAP occupancy of this region, whereas, no enrichment of YAP was found on TLR3 P1." (PMID 35503798, 2022). "Regardless of this, known ligands for TLR3 and TLR5, widely used to mimic bacterial and viral infections, respectively, elicit clear changes in gene expression and the production of cyto/chemokines by individual human embryos." (PMID 34517414, 2021). "Sensing of virus infection (TLR3/7) and IFN-ß expression shows no upregulation in response to virus infection at early time, 3 and 7 dpc, post challenge in brain, liver, spleen or kidney, despite virus titers being high at these time points." (PMID 33230226, 2020). "It is likely that the activation of the pattern recognition receptors, toll-like receptor 3 (TLR3), RIG-1, and MDA-5, after viral infection mediates this response, though this has not been carefully elucidated in this model." (PMID 28536345, 2017). "In this study, we observed the TLR3/TRIF/RIP-1 pathway also involved in TRAF1, TRAF2 and TRAF3 activation, but not TRAF6 after stimulation by dsRNA or viral infection in the corneal epithelium." (PMID 25754842, 2015). "Amantadine had more inhibitory effect on TLR3 gene expression of A549 cells in the presence and absence of H1N1 viral infection compared to TSL-1." (PMID 24073006, 2013). "As the basal level of TLR3 in HUH-7 cells is low, its role in induction of IFN and in restriction of virus infection in this type of cells is not fully appreciated." (PMID 21245912, 2011). "When cells were silenced for only RIG-I and MDA5 (but not TLR3), substantial production of IFN-β was observed upon virus infection and vice versa." (PMID 21245912, 2011). "However, some specific responses to stimulation of TLR4 or TLR3 and RIG-I like receptor were detected that have not previously been annotated as specific for bacterial and viral infection in swine." (PMID 32973863, 2020). "In contrast, the rs3775290 SNP of TLR3 and TLR7 SNPs were not related to viral infection." (PMID 28046022, 2017). "The effect of IAV on nasal secretions could be explained by its stimulation of TLR3-signaling since IN administration of the analog of viral dsRNA, poly-ICLC, was sufficient to increase bacterial shedding in the absence of viral infection." (PMID 27732665, 2016). "However, there is no specific inhibitory effect to the TLR3 and Bcl2-A1 expressions in the absence of H1N1 viral infection by the Amantadine and TSL-1." (PMID 24073006, 2013). "However, the only TLRs that utilize TRIF are TLR3 and TLR4 and the former is likely not involved in C. koseri recognition since its ligand, dsRNA, is typical of viral infections." (PMID 21496301, 2011). "It was suggested that residual RIG-I/MDA5-MAVS pathway-mediated I-IFN production might compensate for the lack of TLR3-IFN response during peripheral viral infections, accounting for the absence of a prior history of severe viral infections in these four patients." (PMID 41608123, 2025). "Although the cells infected by influenza virus do not produce dsRNA, Tlr3−/− mice have a longer lifespan compared with wild-type mice after deadly influenza virus infection, suggesting that TLR3 recognizes an unidentified RNA structure following viral infection." (PMID 34531860, 2021).
COVID-19 (108 papers, 2020 to 2026). A disease caused by infection with severe acute respiratory syndrome coronavirus 2. "In this scenario, a single-nucleotide polymorphism in the Toll-like receptor 3 (TLR3) gene has been linked to the severity of COVID-19." (PMID 41011507, 2025). "-Lower levels of TLR3 expression in peripheral blood have been associated with poorer outcomes in patients with severe COVID-19." (PMID 41011507, 2025). "Heterozygosity for p.Pro554Ser in the TLR3 gene, which increases susceptibility to severe COVID-19, and homozygosity for CCR5 c.554_585del, associated with severe WNV infection, were found." (PMID 38976510, 2025). "Other genetic variants in TLR3, such as rs3775291, have been related to an impairment in the immune response and associated with COVID-19 susceptibility and mortality." (PMID 38605121, 2024). "It has been reported that among patients with severe COVID-19, some have deficiencies in toll-like receptor 3 (TLR3), TLR7, or interferon (IFN) signaling, or possess autoantibodies against type I IFNs." (PMID 39652608, 2024). "A protective role of TLR3 has been reported in infections caused by organisms closely related with COVID-19 viruses, such as SARS-CoV-1 and Middle East respiratory syndrome coronavirus." (PMID 37966347, 2023). "A single subcutaneous injection of Peg-IFNα2 was administered to a 25-year-old woman with known TLR3 deficiency [p.(Pro455Ser)] and COVID-19 who had two episodes of herpes simplex encephalitis in childhood, but had no further serious viral infections." (PMID 37175768, 2023). "Based on free global genomic datasets from worldwide populations, Dhangadamajhi and Routet (2021) investigated the likely association between the TLR3 SNP rs3775291 and COVID-19 and concluded that the SNP is linked to susceptibility to disease and death." (PMID 38173795, 2023). "According to a previous report, TLR3 expression is reduced in the peripheral blood of COVID-19 patients, and this reduction is associated with unfavourable outcome." (PMID 36840831, 2023). "In the present study, we identified two key RNAs (PRL and TLR3) associated with the prognosis of COVID-19." (PMID 37966347, 2023). "Brain inflammatory reactions caused by TLR3 activation are also relevant to understand pathogenic cascades by viral SARS-CoV-2 infection causing post- COVID-19 brain-related syndromes." (PMID 37704739, 2023). "Regarding to COVID-19, to date, only one case-control epidemiological study has been carried out to assess the association between the disease and the TLR3 rs3775290 SNP." (PMID 38173795, 2023). "A new RNA endotype classified using high PRL/TLR3 was associated with mortality in COVID-19 patients." (PMID 37966347, 2023). "Whole exome/genome sequencing based study in 659 cases with severe COVID-19 identified variants in 13 loci, predominantly affecting TLR3 and IRF7 dependent activation of type I IFNs." (PMID 35601440, 2022). "A population based GWAS reported polymorphism in TLR3 gene (rs3775291) was associated with increased susceptibility and death in COVID-19 patients." (PMID 35601440, 2022). "For example, inborn genetic polymorphisms in TLR3-dependent IFN I signaling pathways were associated with COVID-19 life-threatening pneumonia." (PMID 35215785, 2022). "Functional studies in human patients with polymorphisms in TLR3 are needed to conclusively define the role of TLR3 in COVID-19." (PMID 35601440, 2022). "The present data support the possibility that dexamethasone antagonizes the cytokine storm in COVID-19 patients in part by reducing expression of the virus signaling associated receptor TLR3." (PMID 35203701, 2022). "Common coding polymorphisms linked with COVID-19 severity have been identified also in genes of the innate immune system like the TLR3 gene." (PMID 35618891, 2022). "Our data support the possibility of using TLR3 expression to identify patients at risk of life-threatening COVID-19." (PMID 34315957, 2021).
COVID-19 (continued). "In previous studies, TLR3 polymorphisms are associated with severe hepatitis B and C virus infections; currently, these polymorphisms have also been related to COVID-19 severity." (PMID 34803441, 2021). "Critical COVID-19 and seasonal influenza can be caused by inborn errors of TLR3-dependent type I IFN immunity, but susceptibility to these infections is not allelic at the TLR7 locus." (PMID 34413140, 2021). "Recent research in adult SARS-CoV-2 cases has identified associations between severe COVID-19 and several rare genetic variants in genes implicated in TLR3-, TLR7-, and IRF7-dependent IFN type I immunity, including heterozygous variants in the gene TBK14–7." (PMID 34210994, 2021). "Timely activation of TLR3 contributes to the initiation and maintenance of effective immune defense, whereas delayed or dysregulated activation can exacerbate inflammation and increase the risk of a cytokine storm, thereby complicating COVID-19 progression." (PMID 41011507, 2025). "In this sense, the objective of this article was to identify possible associations between the SNPs rs3775291 and rs3775290 of TLR3 and symptoms and severity for COVID-19 in a cohort of professionals who worked in the first pandemic wave in Belém-PA, Brazilian Amazon Region." (PMID 38173795, 2023). "Moreover, TLR3 mutants are predisposed to COVID-19 and influenza infection severity and associated mortality." (PMID 37966347, 2023). "It was shown that the transcript levels of TLR3 were overexpressed in the nasopharyngeal epithelial cells of COVID-19 patients with clinical symptoms compared with controls, and that a lower peripheral blood TLR3 expression was associated with an unfavorable outcome in severe COVID-19 patients." (PMID 37175768, 2023). "Moreover, the presence of the single nucleotide variant (SNV) Rs3775291 in the TLR3 locus has been related to COVID-19 severity, highlighting the importance of this TLR in the immunological recognition of SARS-CoV-2." (PMID 36985262, 2023). "In another work, it was shown that congenital errors in TLR3 and IRF7-dependent type I IFN immunity underlie critical COVID-19, demonstrating the essential role of both the TLR-3 double-stranded RNA sensor and intrinsic immunity to type I IFNs in controlling SARS-CoV-2 infections in the lungs." (PMID 36297256, 2022). "However, in this work, the associations between the STAT2 variant 12-56744928-GA and the TLR-3 variant 12-56744928-GA with severe COVID-19 and mild COVID-19, respectively, were detected." (PMID 35062298, 2022). "In addition, a TLR3 (rs3775290) polymorphism has been associated with an increased risk of pneumonia in patients with COVID-19." (PMID 36419185, 2022). "Given the protective role of TLR3 in other infectious diseases, an association between the functional variation in its gene and COVID-19 incidence was hypothesized." (PMID 35618891, 2022). "Additionally, reduced expression of TLR3 in peripheral blood has been associated with worse outcomes in patients with severe COVID-19." (PMID 36419185, 2022). "The polymorphism L412 in TLR3 inhibited autophagy and made males at risk of severe COVID-19." (PMID 36204639, 2022). "Therefore, any COVID-19 vaccine that contains adjuvant or pathogen antigen molecule mimicking dsRNA can activate the TLR3 pathway and perhaps cause an autoimmune response against acetylcholine receptors." (PMID 36164665, 2022). "Serum IFN-a levels may be found to be very low in some COVID-19 cases due to TLR3 or IRF3 polymorphisms." (PMID 34803441, 2021). "Strikingly, combined stimulation of anti-spike IgG immune complexes and the toll-like receptor 3 agonist, polyinosinic:polycytidylic acid (poly(I:C)) increased the production of COVID-19-associated pro-inflammatory cytokines IL-1β, IL-6, and TNF compared to IgG or poly(I:C) alone." (PMID 33979301, 2021).
COVID-19 (continued). "However, conflicting reports on TLR3 expression in critically ill patients reflect the complexity of its role as a critical mediator of the immunoprotective and immunopathogenic consequences associated with COVID-19." (PMID 41011507, 2025). "Therefore, the association between reduced TLR3 expression and mortality revealed in the present study may reflect the consequences of impaired immune defense against COVID-19." (PMID 37966347, 2023). "Therefore, elucidating the circadian clock regulation of TLR3 signaling in the alveolar microenvironment is crucial in exploring mechanisms by which the disruption of the circadian rhythms increases the risk of developing COVID-19." (PMID 35281442, 2022). "Finally, severe COVID-19 in previously healthy individuals may result from monogenic predisposition, monogenic inborn errors of immunity of Toll-like receptor 3 (TLR3), and type I IFN cell-intrinsic immunity." (PMID 35466178, 2022). "Moreover, TLRs are involved in the activation of the immune response causing a cytokine storm in COVID-19 patients, where TLR-3, -7, -8 through viral RNA recognition triggers the activation of JAK/STAT, NF-kB, AP-1 signaling pathways resulting in the amplification of pro-inflammatory cytokines." (PMID 34975904, 2021). "We previously tested the hypothesis that critical influenza and critical COVID-19 can be allelic, and showed that life-threatening COVID-19 pneumonia can be caused by rare inborn errors of autosomal genes controlling TLR3- and IRF7-dependent type I interferon (IFN) immunity." (PMID 34413140, 2021). "-Neutrophils from patients with severe COVID-19 exhibit higher levels of TLR3 and TLR7 than those from healthy donors.-TLR3 gene expression was found to be significantly higher in critically ill SARS-CoV-2 patients than in those with mild disease." (PMID 41011507, 2025). "The genetic analysis identified the TLR3 p.Pro554Ser variant in the patient, who experienced severe WNV encephalitis and severe COVID-19, and in his daughter, who had a mild COVID-19 infection, supporting an incomplete clinical penetrance." (PMID 38976510, 2025). "In this context, the following TLRs have been associated with the severity of COVID-19: TLR2, TLR3, TLR4, TLR7, TLR8 and TLR9." (PMID 41011507, 2025). "In our previous work, we observed increased frequencies of TLR3, TLR7, and TLR8 variants among severe and critical COVID-19 cases." (PMID 40943412, 2025). "In Ea.hy926 endothelial cells, xenoAMPs-poly(I:C)-induced TLR3-mediated tissue factor (TF) production can in principle be related to observation of amplified coagulation in COVID-19." (PMID 38306481, 2024). "The purpose of this data was to investigate TLR3, 7, and 8 expression levels in COVID-19 patients and their relationship to outcome of disease." (PMID 38868379, 2024). "The data showed a significant difference (p = 0.01) in the TLR3 transcript levels between critical and mild COVID-19 patients." (PMID 38868379, 2024). "For further analysis, we compared the PRL and TLR3 in plasma of 54 COVID-19 patients and 20 healthy subjects." (PMID 37966347, 2023). "Moreover, a reduced survival rate at 28 days was shown in L412F COVID-19 patients treated with the autophagy-inhibitor hydroxychloroquine, suggesting that the outcome of clinical trials with hydroxychloroquine should be reinterpreted in the light of the TLR3-L412F polymorphism status." (PMID 37175768, 2023). "Levy and collaborators reported the safety of a single subcutaneous injection of Peg-IFN-α2a in two patients with inborn errors of the TLR-3 and IRF-7, affecting the production of type I IFNs and predisposing to severe COVID-19." (PMID 38288121, 2023). "In this study, whole-blood RNAs (prolactin and toll-like receptor 3) involved in the prognosis of patients with COVID-19 were identified." (PMID 37966347, 2023).
COVID-19 (continued). "Another study reported decreased functioning of DCs from COVID-19 patients towards TLR triggers during acute SARS-CoV-2 infection as DC activation upon TLR3, TLR4, TLR7 and TLR8 triggering was suppressed." (PMID 37844099, 2023). "Comparative genotyping analysis of this cohort for the TLR3 SNP rs3775291 and rs3775290 related to COVID-19 severity." (PMID 38173795, 2023). "Few data are available concerning TLR3 levels in COVID-19 patients, but it has been shown that TLR3 activates type I/III IFNs through the TRIF factor." (PMID 36985262, 2023). "Rare variants of TLR3- and TLR7-dependent type I IFN immunity genes can underlie life-threatening COVID-19, particularly with recessive inheritance, in patients under 60 years old." (PMID 37020259, 2023). "In contrast, increased expression of TLR3 (p = 0.033) was observed in BAL cells of COVID-19 patients who had pulmonary bacterial superinfections." (PMID 36985262, 2023). "This is further supported by a study which analyzed patients with severe COVID-19 and showed a positive correlation between the severity of disease and TLR3 inborn errors." (PMID 36419185, 2022). "In particular, autosomal-recessive deficiencies in IRF7 and IFNAR1 and autosomal-dominant deficiencies in TLR3, TBK1, IRF3, IRF7, IFNAR1 and IFNAR2 genes have been found in a small percentage of patients with severe influenza and COVID-19." (PMID 35846766, 2022). "Consistent with this, rare pathogenic variants in TLR7 and eight candidate loci, including, TLR3, IRF3, and IRF7 governing type I IFN response have been identified in patients with critical COVID-19." (PMID 36143338, 2022). "Of note, albeit TLR3 activation is critical for viral clearance, TLR3 hyperactivation can lead to a cytokine storm and the subsequent severe COVID-19." (PMID 35577935, 2022). "We found that COVID-19 plasma exosomes significantly induced the expression of TLR3 and TLR9 in all subsets of immune cells tested, while COVID-19 plasma exosomes were unable to induce TLR7 expression in CD8+ T cells." (PMID 36526691, 2022). "Meanwhile, studies investigating single gene inborn errors have identified toll-like receptor 3 (TLR3), TLR7, and type I interferon immunity in predisposing individuals to critical COVID-19 illness." (PMID 36263375, 2022). "Genetic mutations TLR3, TLR7, and IRF7-dependent and neutralizing autoantibodies inhibited type I interferon signaling in COVID-19 patients who had severe disease." (PMID 36726976, 2022). "For instance, people with a mutation of TLR3 or IFN-α receptor and with autoantibody against IFN-α have a higher risk of COVID-19 exacerbation." (PMID 35281442, 2022). "Among the extracted ultra-rare variants there was a group of genes, such as TLR3, TLR7 and TICAM1, already shown to be directly involved in the Mendelian-like forms of COVID-19." (PMID 34889978, 2022). "Here, we demonstrate that lower expression of TLR-3 and an enhanced expression of TLR-4 are associated with an unfavorable outcome in COVID-19 patients." (PMID 34315957, 2021). "When comparing COVID-19 MILD and COVID-19 SEVERE groups, a decreased expression of TLR3, accompanied by a deficient IFN-γ and an enhanced TLR4 expression were associated with an unfavorable outcome." (PMID 34315957, 2021). "The difference between COVID-19 MILD and COVID-19 SEVERE TLR3 and TLR4 mRNA expression at admission widened during follow-up." (PMID 34315957, 2021). "Our study suggests that L-pampo, a combination of TLR1/2 and TLR3 agonists, can be a potent adjuvant system for subunit vaccines against COVID-19." (PMID 34579194, 2021). "Further research is necessary to understand the potential of modulating TLR3 expression as a method to prevent or treat COVID-19." (PMID 34315957, 2021). "In this sense, HCQ can inhibit endosomal TLR3, -7, -8, and -9 signaling, controlling inflammation in COVID-19 patients and mitigating the detrimental effects of viral infection." (PMID 34975904, 2021).